SPHK2 (sphingosine kinase 2)
Diseases named in the same sentence as SPHK2 in open-access papers (continued):
Sharing a sentence is not in itself a finding about the gene and the disease.
cancer (continued). "In general, there is a controversy surrounding the role of SphK2 in cancer pathogenesis and treatment response with some studies showing pro-apoptotic and anti-tumorigenic functions of SphK2 and others indicating a pro-survival and oncogenic role." (PMID 32456134, 2020). "The role of SPHK2 in cancer is more controversial, with evidence showing both oncogenic and anti-cancer effects." (PMID 32260399, 2020). "Despite this, SphK2 has been recognized as overexpressed in many human cancers, and low-level SphK2 overexpression has been shown to promote cell proliferation and survival." (PMID 32796926, 2020). "This is because AKT, SPHK1, and SPHK2 are reported to be involved in cancer cell growth and resistance." (PMID 31817453, 2019). "The second, ABC294640, a selective SphK2 inhibitor, effectively reduced the levels of S1P and inhibited the growth of multiple cancers in vitro and in preclinical xenograft studies." (PMID 31807117, 2019). "In general, SphK1 is tumor promoting and SphK2 is suppressive; SphK1 is upregulated in cancer, while SphK2 is downregulated." (PMID 29987226, 2018). "Compared to the extensively investigated SPHK1 isoform, the functions and mechanisms of SPHK2 in cancer remain largely elusive and the roles of SPHK2 in cancer cells are not fully understood with inconsistencies in published data." (PMID 31891125, 2018). "SphK2 inhibitors are now in phase II clinical trials for a number of cancers including B cell malignancies, following successful completion of phase I studies." (PMID 29441205, 2018). "Knockdown of SphK2 expression increases the sensitivity of cancer cells to chemotherapy, while chemical inhibition can reduce cancer cell growth in vitro and in pre-clinical animal models." (PMID 29441205, 2018). "Moreover, treatment with exosomes from primary hepatocytes could effectively increase hepatocyte proliferation and liver regeneration through upregulation of Sphk233, and high levels of SphK2 have been confirmed to be associated with cancer growth and insensitivity to chemotherapy." (PMID 29410409, 2018). "The growing evidence supporting a role for SphK2 in cancer development provides sufficient precedent to warrant the inclusion of SphK2 as a candidate therapeutic target for many types of cancer." (PMID 28415564, 2017). "Western blot confirmed that, compared to the distant normal tissues, SphK2 protein expression in NSCLC cancer tissues were higher." (PMID 28428733, 2017). "SPHK2 can be one of the targets for cancer treatment as SPHK2 functions as the pro-survival molecule in tumor growth and metastasis." (PMID 29145490, 2017). "There is now supporting evidence to suggest that aberrant expression and/or inappropriate cellular localization of SphK1 and SphK2 isoforms contribute to both oncogenicity and anti-cancer treatment resistance." (PMID 28415564, 2017). "Similar results were also obtained in MG63 cells, where over-expression of SphK2 facilitated cancer cell growth." (PMID 29285269, 2017). "There is a strong drive for SphK2 inhibitors given that they appear to be more efficacious than SphK1 inhibitors in in vitro cancer cell line studies and cancer clinical trial studies, in particular the SphK2 inhibitor ABC294640." (PMID 28869494, 2017). "It is important to note that along with SphK1, SphK2 is overexpressed in many human cancers and based on its cellular localization it can function as a pro- or antiapoptotic signaling molecule." (PMID 29269995, 2017). "As recently reviewed by McGowan and colleagues, SphK2 is gaining acceptance as a valid cancer therapeutic target and specific SphK2 modulators (agonists and antagonists) appear to have increased efficacy in clinical trials for cancer treatment." (PMID 28869494, 2017). "Although early studies have proposed a possible pro-apoptotic/anti-cancer function by of SphK2, emerging recent evidences have confirmed that SphK2, like SphK1, is also oncogenic." (PMID 29285269, 2017).
cancer (continued). "There is undisputable evidence to support a significant role for aberrant SphK1 and SphK2 isozyme expression in cancer development." (PMID 28415564, 2017). "ABC294640 is a novel Sphk2 specific inhibitor with high efficacy in several preclinical models of cancer and synergistic anticancer activity with chemotherapies or molecular targeted therapies." (PMID 26956050, 2016). "Altogether, these evidences unwrap a new opportunity to consider SphK2 as a potential target, not only to inhibit cancer progression but also to prevent tumor resistance to standard chemotherapy." (PMID 27800303, 2016). "A recently developed first-in-class Sphk2 specific inhibitor ABC294640 displays antitumor activity in many cancer models." (PMID 26956050, 2016). "In contrast to the substantial evidences that suggest a crucial role of SphK1 in cancer development, much less is known about the function of SphK2." (PMID 27800303, 2016). "Although the role of SphK1 in cancer progression has been extensively studied in the literature, the function of SphK2 on cell survival, growth and drug resistance has only recently been elucidated." (PMID 26337959, 2015). "Patient-2-derived cancer cells had highest level of SphK2, these cells were extremely sensitive to ABC294640-induced growth inhibition and cell death." (PMID 26337959, 2015). "On the other hand, patient-1-derived cancer cells had lowest SphK2 level, the cytotoxic effect of ABC29464 was also relatively weak in those cells." (PMID 26337959, 2015). "Recently, HDAC has been identified as an intracellular target of S1P, which is mainly produced by SphK2 within the nucleus and indicates a potential role of SphK2 in histone acetylation, gene expression, and cancer pathology." (PMID 23437140, 2013). "SphK1 and SphK2 have both been implicated in tumorigenesis; however, there is much less evidence for SphK2 involvement in cancer." (PMID 23028939, 2012). "Recently, a crucial role in the cancer progression of S1P elicited by SphK2 has been shown." (PMID 39940821, 2025). "Sphingosine kinases (SphK1 and SphK2) are key regulators of sphingolipid signaling, a pathway essential for maintaining cell structure and function but frequently deregulated in tumors, making them promising targets for cancer therapy." (PMID 40427516, 2025). "Functional studies have shown that knockdown of SphK2 expression or use of selective inhibitors can significantly inhibit cancer cell proliferation, migration, and invasion, with mechanisms involving induction of apoptosis and enhanced chemotherapy sensitivity." (PMID 41234914, 2025). "In contrast to SphK1, SphK2’s role in cancer is not fully understood." (PMID 39940821, 2025). "Therefore, SphK1, SphK2, and their product S1P have become potential therapeutic targets for the treatment of various diseases, especially cancer cells." (PMID 41234914, 2025). "Therefore, targeting SphK1, and SphK2 by using inhibitors to produce low levels of S1P can be a novel protocol to minimize the cancer cell's resistance towards chemotherapeutic drugs." (PMID 38419070, 2024). "The S1P protein produced by SPHK2 binds to receptors on the cell membrane to achieve allosteric-mimicking protein phosphorylation, which increases the stability and function of telomerase, thereby producing a protective effect in cancer cells." (PMID 35846357, 2022). "Earlier studies have shown that SphK2 regulates c-Myc in a number of cancer cells." (PMID 35178477, 2022). "Although SPHK2 may be cytoprotective in some cancers, research has focused on developing small-molecule SPHK2 inhibitors that kill malignant cells or inhibit cancer growth." (PMID 34055895, 2021). "Contrary to the notion that SphK2 has apoptotic functions, several experimental studies have suggested an essential role of this isoenzyme in cell proliferation and survival similar to SphK1 in cancer cells." (PMID 33920887, 2021).
cancer (continued). "In cardiomyocytes and cancer cell lines, SPHK2 is also found in mitochondria, indicating that S1P may have a role in these organelles as well." (PMID 34055895, 2021). "SPHK2 is involved in tumorigenesis of diverse types of cancers." (PMID 34055895, 2021). "Finally, SPHK2 is a nuclear enzyme in many cell types, including various cancer cell types, fibroblasts, and neurons." (PMID 34055895, 2021). "Overexpression of SPHK2 was reported to suppress cell growth and induce apoptosis by sequestration of BCL2 by its BH3 domain, while siRNA-mediated loss of SPHK2 from cancer cells produced a strong anti-cancer effects." (PMID 32260399, 2020). "Targeting SPHK2 demonstrates antitumorigenic effects in cancer cell lines and mouse models." (PMID 32887262, 2020). "Since SphK2 has been implicated in the modulation of several forms of cancer, it is not altogether surprising that SphK2 has been shown to play a role in latency for the oncogenic virus Kaposi’s sarcoma-associated herpesvirus (KSHV)." (PMID 31783527, 2019). "Since SPHK1 and SPHK2 have equipotent effects in cancer metastasis and resistance, inhibiting these enzymes could decrease cancer cell growth and prevent cancer cell resistance." (PMID 31817453, 2019). "Interestingly, in cancer models, retinoic acid signaling was found to be deregulated by nuclear SphK2/S1P signaling, with S1P acting as an antagonist for the retinoic acid receptor (RAR) beta." (PMID 29615132, 2018). "We found that the transfected SphK2 mainly resided in the nuclei of cancer cells." (PMID 28465486, 2017). "Interestingly, hSphK2 ablation using RNA interference technology was shown to be more efficacious in inducing cell death validating both SphK1 and SphK2 as targets for anti-cancer treatment." (PMID 28415564, 2017). "Therefore, SPHK1 and SPHK2, two enzyme essential for S1P generation, as well as S1P itself and S1P receptors, have been recognized as promising targets for cancer treatment." (PMID 29208982, 2017). "Hence, the term drugging the addict(s) (SphK1, SphK2 and S1PRs) has been the driving force for novel cancer drug design." (PMID 28415564, 2017). "Interestingly, this simplistic viewpoint has shifted and recent emerging functions of SphK1 and SphK2, relevant to the newly emerging SphK-targeting cancer therapies, will be discussed." (PMID 28415564, 2017). "SphK2 is also gaining ground as a marker of cancer progression." (PMID 28415564, 2017). "In recent years, strong evidence supports the overexpression of SphK2 in many human cancers." (PMID 28869494, 2017). "Indeed, the dichotomy of the individual roles of SphK1 and SphK2 are even more blurred when it comes to more aggressive cancers or metastasis and treatments which target SphK1 and/or SphK2." (PMID 28869494, 2017). "Accumulating reports show that high expression of SphK2 is frequently occurs in many cancers." (PMID 28465486, 2017). "A recent study has suggested that miRNA could inhibit cell proliferation and induce apoptosis of cancer cells by targeting sphingosine kinase 2 (SphK2), a factor promoting tumor progression." (PMID 28947960, 2017). "Recent studies have proposed that SphK2 is over-expressed in many cancer cells." (PMID 29285269, 2017). "SphK1, which is an oncogenic kinase, is involved in tumor development and progression of various human cancers but biological functions of SphK2 in NSCLC remain unknown." (PMID 28428733, 2017). "Our study suggests that STAT3 may also be a downstream target of S1P that is generated from Sphk2, which may mediate its pro-survival effect in cancer." (PMID 26956050, 2016). "Sphingosine kinase 2 (Sphk2) has an oncogenic role in cancer." (PMID 26956050, 2016). "Cancer studies with SphK2 are less common than those with SphK1." (PMID 27129720, 2016). "Reports on SPHK2 in the context of cancer are fewer and more conflicting." (PMID 24970218, 2014).
cancer (continued). "The mechanism by which SphK2-produced S1P acts as an endogenous HDAC inhibitor might suggest a more sophisticated role of SphK2 in cancer progression due to the varied contexts of epigenetic regulation among different cell types." (PMID 24286034, 2013). "Notably, targeted inhibition of SphK2 exhibits more significant anticancer effects than SphK1 in various cancer cell lines, and gene knockout experiments have confirmed that the anticancer effect of SphK2 deletion is far superior to that of SphK1 or dual enzyme inhibition." (PMID 41234914, 2025). "Additionally, SphK2 is often overexpressed in many types of cancer." (PMID 36982369, 2023). "Thus, further exploration of the roles and mechanisms of SphK2 in cancers may provide a better suggestion in cancer treatment." (PMID 34305532, 2021). "Hence, further exploration of the roles and mechanisms of SphK2 in cancers may provide a better suggestion in cancer treatment." (PMID 34305532, 2021). "Moreover, SphK2 may participate in mast cell function, with SphK2 inhibition ameliorating immunosuppression-related disorders, such as chronic infections and/or cancers." (PMID 31807117, 2019). "As genetic alteration and aberrant metabolism are two of the hallmarks of cancer, the link between overexpression of SphK2/S1P in the nucleus, affecting genetic gene regulation and stability, and SphK2/S1P altering mitochondria metabolism, may have consequences for cancer progression." (PMID 28415564, 2017). "Thus, targeting SphK2 should have therapeutic potential for treating cancer." (PMID 29285269, 2017). "The SphK2 isozyme is gaining much prominence as a cancer therapeutic target and may prove to have greater efficacy as an oncotarget than its comparative isozyme hSphK1, which is driving the development of the hSphK2 inhibitors, and the ongoing clinical trials of the hSphK2 ABC294640." (PMID 28415564, 2017). "Also there is some in vitro data to suggest that SphK2 can compromise the integrity of the endothelial cell monolayer, which may contribute to invasion and migration of cancer cells." (PMID 28415564, 2017). "Therefore, targeting Sphk2 appears to have therapeutic potential for treating cancer." (PMID 26956050, 2016). "On the other hand, the role of SPHK2 in cancer is still largely unknown." (PMID 25153718, 2014). "There is a known correlation between cancer and changes in sphingolipids, particularly the production of S1P by SPHK1 and SPHK2." (PMID 41234914, 2025). "Our findings demonstrate the SphK2/CERT axis as a novel therapeutic target for NAFLD-HCC, although the intricate role of these coupled lipid regulators in different cancer contexts warrants further investigation." (PMID 36333295, 2022). "Both SphK1 and SphK2 play crucial roles in tumorigenesis and progression of NSCLC and other human cancers, mainly by regulating cell proliferation and apoptosis." (PMID 35831279, 2022). "Moreover, the SphK1/SphK2 product, S1P was shown to target histone deacetylases (HDAC1/2), tumor necrosis factor receptor associated factor 2 (TRAF2), human telomerase reverse transcriptase (hTERT), and NF-κB nuclear activities linked to cancer initiation and progression." (PMID 33919234, 2021). "SPHK2 has basal activity towards sphingosine; however, SPHK2 can be activated by a variety of factors and conditions, including epidermal growth factor (EGF) in cancer cells Pyne and Pyne (2020) and hypoxia in cerebral microvascular endothelial cells." (PMID 34055895, 2021). "Preclinical studies have adduced a wealth of evidence to support the ability of specific SphK2 inhibitor ABC294640, which is currently being tested in cancer patients in phase I/II clinical trials, to increase cancer cell response to chemotherapy." (PMID 32456134, 2020).
cancer (continued). "Anti-intuitively, despite increased S1P levels in these experiments, reduction of SphK2 suppressed proliferation and migratory potential of cells more effectively than SphK1 ablation indicating targeting SphK2 may have stronger anti-cancer effects in cancer therapy." (PMID 28415564, 2017). "Strategies that have been applied to limit the effects of SPHK1-S1P signaling in cancer include inhibition of SPHK1 and/or SPHK2 and targeting of specific S1P receptors." (PMID 26311741, 2015). "In contrast to SphK1, SphK2’s role in disease, and in particular in cancer, is not fully understood." (PMID 39940821, 2025). "Several other modulators, such as the dual inhibitors of SPHK1 and SPHK2, N,N-dimethylsphingosine (DMS) and SKI-II, the SPHK2 antagonist opaganib (ABC294640), the S1PR1 and S1PR3 antagonist VPC23019, and the S1PR2 agonist CYM5520, have been extensively utilized in cancer treatment and research." (PMID 39519028, 2024). "S1P is intracellularly produced in cancer cells and non-cancer stromal cells from sphingosine by two sphingosine kinases (sphingosine kinase 1 (SphK1) and 2 (SphK2)) and then exported to the TME." (PMID 39835329, 2024). "Thus, we proposed that NEDD4L can inhibit Akt activation in ccRCC possibly through degrading its upstream activators such as STK35, SphK2, CTR1, and PIK3CA, which were previously reported in different cancers." (PMID 37580757, 2023). "As shown treatment with SKI-178 (10 μM, 24 h) failed to affect mRNA expression of SphK1 and SphK2 in pCan1 primary cancer cells." (PMID 37604912, 2023). "Human SPHK2 is phosphorylated at Ser351 and Thr578 by extracellular signal-regulated kinase 1 (ERK1), and phosphorylation of these residues is important for EGF-mediated migration of cancer cells." (PMID 34055895, 2021). "Various cancer cell lines exhibit cytotoxicity or lowered proliferation and migration due to lack of the activity of SPHK2." (PMID 34055895, 2021). "Importantly, ABC294640 is a structural analog of SKI-II, which was developed to be more selective for SPHK2 than for SPHK1, and is currently in clinical trials for cancer chemotherapy." (PMID 34033645, 2021). "The expression of SPHK2 and SGPL1 were downregulated in cancer compared to normal tissue." (PMID 32630814, 2020). "S1P produced by SPHK1, not SPHK2, is exported out of cancer cells through transporters, and act in paracrine and autocrine manner, which is known as “inside-out signaling”12." (PMID 30018456, 2018). "Previously we reported that S1P produced by SPHK1, but not SPHK2, is a critical mediator of cancer-induced lymphangiogenesis." (PMID 30018456, 2018). "Because sphingosine kinase 1 and sphingosine kinase 2 (SPHK 1/2) are both essential for sphingosine-1-phospate production, they could be a therapeutic target in various cancers." (PMID 29208982, 2017). "Despite abundant reports strongly suggesting that S1P is associated with cancer progression, few findings obtained with a selective inhibitor of SphK1 or SphK2 however suggested that they are not involved in cell growth of cancer cells." (PMID 29269995, 2017). "On the other hand, the potential function of SphK2 in human cancers has not been extensively studied until recently." (PMID 29285269, 2017). "However, the predominance of SPHK1 in the context of cancer is supported by the observation that SPHK1 is up-regulated, whilst SPHK2 is downregulated, as a function of glioma malignancy." (PMID 24970218, 2014). "A recent study has proposed a new SphK2 specific inhibitor ABC294640 which reduces S1P levels and inhibits cancer cells proliferation in vitro and in vivo, and might be used to further dissect the biological functions between the two isoforms." (PMID 24286034, 2013). "miR-613 could inhibit cancer cell proliferation, migration, invasion and promotes apoptosis by targeting numerous oncogenes, including DCLK1, Fzd7, and SphK2.miR-613 had been stated to be down-regulated in different cancers and act as a tumor suppressor." (PMID 32592365, 2020).